KRT83 (keratin 83)
Description:
Structural component of intermediate filaments in the hair cortex. Forms obligate heterodimers with type I hair keratins, which assemble into keratin intermediate filaments that contribute to the structural integrity and mechanical strength of the hair shaft.
Synonyms: KRTHB3; Hb-3; EKVP5; HB3; MNLIX; MNLIX3
Tractability: PROTAC: UniProt records ubiquitination sites on it; ubiquitination databases record sites on it.
Target class: Structural protein
Gene: Protein-coding gene on chromosome 12 (52,314,301 to 52,321,398, reverse strand). Ensembl gene ENSG00000170523.
Pathways (Reactome):
Developmental Biology: Formation of the cornified envelope; Keratinization
Gene Ontology:
Molecular function: protein binding; structural constituent of skin epidermis
Biological process: hair cycle; epidermis development; intermediate filament organization; keratinization
Cellular component: extracellular region; cytosol; keratin filament
Genetic constraint (gnomAD): Loss-of-function variants: 51 observed, 52.54 expected, observed/expected ratio (o/e) 0.97, 90% interval 0.77 to 1.23. The upper end of that interval is the gene's LOEUF score, 1.23, which puts it in group 5 of 6, group 1 being the genes least tolerant of losing a copy. Missense variants: 654 observed, 669.74 expected, observed/expected ratio (o/e) 0.98, 90% interval 0.92 to 1.04. Synonymous variants: 278 observed, 270.88 expected, observed/expected ratio (o/e) 1.03, 90% interval 0.93 to 1.13.
Homologues: Orthologues: dog KRT81 (89% identical), chimpanzee KRT83 (87% identical). Paralogues in human: KRT81 (95% identical), KRT86 (90% identical), KRT85 (82% identical), KRT84 (63% identical), KRT82 (57% identical), KRT5 (51% identical), KRT6A (50% identical), KRT6C (50% identical), KRT6B (50% identical), KRT75 (49% identical), KRT3 (49% identical), KRT8 (47% identical), and 56 more.
Diseases named in the same sentence as KRT83 in open-access papers:
KRT83 is named in the same sentence as 12 diseases in open-access papers, as found by Europe PMC text mining. Sharing a sentence is not in itself a finding about the gene and the disease. The quoted sentences say what the papers report.
monilethrix (2 papers, 2011 to 2022). Monilethrix is a rare genodermatosis characterized by a hair shaft dysplasia resulting in hypotrichosis. "Specifically, mutations in the 1A and 2B domains of KRT81, KRT83, and KRT86 resulted in Monilethrix, a rare monogenic hair loss disorder 28,35." (PMID 35145093, 2022). "In this study, we have identified a Chinese family with monilethrix, and sequenced three keratin genes (KRT81, KRT83, and KRT86) of the subjects to elucidate the underlying molecular basis of this disorder." (PMID 23554671, 2011).
breast tumours (1 paper, 2015). "We found that all ten EMT-related genes were frequently methylated in primary breast tumours, i.e. CLDN18 (100 %), KRT85 (100 %), MIR127 (100 %), MIR433 (100 %), MIR23b (60 %), KRT83 (100 %), MST1R (60 %), BVES (60 %), CLDN6 (50 %) and HOXD10 (55 %)." (PMID 26052355, 2015).
KRT83 also shares sentences with these, for which no sentence is quoted: infection (2 papers); achromatopsia (1); bladder cancer (1); echovirus infection (1); epidermolysis bullosa simplex (1); gastric carcinoma (1); hypotrichosis (1); measles (1); pachyonychia congenita (1); rubella (1).